SCAMP2 (secretory carrier membrane protein 2)
Description:
Functions in post-Golgi recycling pathways. Acts as a recycling carrier to the cell surface.
Tractability: Antibody: UniProt predicts a signal peptide or a membrane-spanning region. PROTAC: ubiquitination databases record sites on it; its protein half-life has been measured.
Gene: Protein-coding gene on chromosome 15 (74,843,728 to 74,873,374, reverse strand). Ensembl gene ENSG00000140497.
Subcellular location: Golgi apparatus, trans-Golgi network membrane; Recycling endosome membrane
Subcellular location (Human Protein Atlas): Golgi apparatus; Vesicles; Mid piece; Principal piece
Gene Ontology:
Molecular function: protein binding
Biological process: protein transport; exocytosis; post-Golgi vesicle-mediated transport
Cellular component: extracellular exosome; Golgi apparatus; membrane; recycling endosome membrane; trans-Golgi network membrane
Genetic constraint (gnomAD): Loss-of-function variants: 22 observed, 38.81 expected, observed/expected ratio (o/e) 0.57, 90% interval 0.4 to 0.81. The upper end of that interval is the gene's LOEUF score, 0.81, which puts it in group 3 of 6, group 1 being the genes least tolerant of losing a copy. Missense variants: 341 observed, 384.82 expected, observed/expected ratio (o/e) 0.89, 90% interval 0.81 to 0.97. Synonymous variants: 148 observed, 152.94 expected, observed/expected ratio (o/e) 0.97, 90% interval 0.85 to 1.11.
Homologues: Orthologues: chimpanzee SCAMP2 (99% identical), pig SCAMP2 (93% identical), guinea pig SCAMP2 (89% identical), mouse Scamp2 (89% identical), macaque SCAMP2 (88% identical), rat Scamp2 (88% identical), dog SCAMP2 (87% identical), tropical clawed frog scamp2 (72% identical), zebrafish scamp2l (64% identical), zebrafish scamp2 (63% identical), Drosophila melanogaster Scamp (39% identical), Caenorhabditis elegans scm-1 (36% identical). Paralogues in human: SCAMP1 (55% identical), SCAMP3 (52% identical), SCAMP5 (33% identical), SCAMP4 (28% identical).
Diseases named in the same sentence as SCAMP2 in open-access papers:
SCAMP2 is named in the same sentence as 17 diseases in open-access papers, as found by Europe PMC text mining. Sharing a sentence is not in itself a finding about the gene and the disease. The quoted sentences say what the papers report.
acute myeloid leukemia (3 papers, 2021 to 2025). Acute myeloid leukemia (AML) is a group of neoplasms arising from precursor cells committed to the myeloid cell-line differentiation. "Although reports on SCAMP2 are currently limited, the only study suggesting SCAMP2/5 as diagnostic and prognostic markers for acute myeloid leukemia." (PMID 40406117, 2025). "Recent studies reported that SCAMP2/4/5 could be potential prognostic markers for acute myeloid leukemia (AML)." (PMID 35216324, 2022).
bladder cancer (1 paper, 2025). "Further qPCR results indicated that knockdown of SCAMP2 in two bladder cancer cell lines significantly reduced the expression of these genes." (PMID 40406117, 2025). "The further cell apoptosis assay revealed that SCAMP2 knockdown significantly increased the cell apoptosis induced the treatment of 2 μM cisplatin in T24 and 6783 bladder cancer cells." (PMID 40406117, 2025). "The further in vivo and in vitro experiments also confirmed the regulatory role of SCAMP2 in bladder cancer drug resistance and proliferation." (PMID 40406117, 2025). "The further in vivo experiments were conducted to evaluate the regulatory effect of SCAMP2 overexpression on cisplatin sensitivity in bladder cancer tissues." (PMID 40406117, 2025). "Our study reveals that SCAMP2, as a gene with the highest coefficient in our model, exhibits elevated expression in bladder cancer and holds significant biological significance." (PMID 40406117, 2025). "Further functional assays revealed that SCAMP2 mediates drug resistance in bladder cancer cells via the NOTCH signaling pathway." (PMID 40406117, 2025). "SCAMP2 was identified as a critical gene with elevated expression in bladder cancer, showing strong correlation with sensitivity to multiple anti-cancer drugs, including cisplatin." (PMID 40406117, 2025). "Additionally, in vivo experiments showed that SCAMP2 overexpression significantly enhanced cisplatin sensitivity in bladder cancer tissues." (PMID 40406117, 2025). "The EdU assay demonstrated that SCAMP2 knockdown could significantly inhibit the proliferation of bladder cancer cells." (PMID 40406117, 2025). "Additionally, statistical analysis of the proportion of Ki67-positive cells indicated a significant increase in the proportion of Ki67-positive cells in the SCAMP2 overexpression group, further supporting the critical role of SCAMP2 in regulating cisplatin sensitivity in bladder cancer tissues." (PMID 40406117, 2025). "In our study, SCAMP2 overexpression was found to promote the EMT process, evidenced by the downregulation of the epithelial marker CDH1 and the upregulation of the mesenchymal marker CDH2, thereby enhancing cisplatin resistance in bladder cancer." (PMID 40406117, 2025). "Additionally, we overexpressed SCAMP2 and/or added the NOTCH pathway inhibitor IMR-1 in bladder cancer cells treated with 1 μM cisplatin." (PMID 40406117, 2025).
COVID-19 (1 paper, 2024). A disease caused by infection with severe acute respiratory syndrome coronavirus 2. "Compared to healthy controls, individuals with post-COVID-19 revealed a high percentage of TMEM119+P2RY12+CD68+Iba1+HLA-DR+CD11c+SCAMP2+ microglia assembled in prototypical cellular nodules." (PMID 39060438, 2024).
glaucoma (1 paper, 2023). Increased pressure in the eyeball due to obstruction of the outflow of aqueous humor. "HSP90AB1, RCOR3, SCAMP2 and SLC64A (AUC < 0.8) showed poor ability to distinguish POAG from non-glaucoma individuals." (PMID 37940950, 2023).
glioma (1 paper, 2023). A benign or malignant brain and spinal cord tumor that arises from glial cells (astrocytes, oligodendrocytes, ependymal cells). "It should also be noted that the function of KCNC1, KCNT1, RIMS2, NECAP2, GNG5, SCAMP2, GNAI3 genes is also correlated with membrane function in low-grade gliomas." (PMID 37239411, 2023).
leukemia (1 paper, 2021). A malignant (clonal) hematologic disorder, involving hematopoietic stem cells and characterized by the presence of primitive or atypical myeloid or lymphoid cells in the bone marrow and the blood. "To better understand the potential biological mechanisms between SCAMP2/4/5 and leukemia, we used Metascape to generate the PPI network of the gene set, and found several significant MCODE components from the PPI network according to the clustering scores." (PMID 34426610, 2021). "Similarly, the transcriptional level of SCAMP2 was significantly upregulated in patients with leukemia in three datasets." (PMID 34426610, 2021).
scleroderma (1 paper, 2021). Scleroderma is a rare autoimmune connective tissue disorder characterized by abnormal hardening of the skin and, sometimes, other organs. "We note 38 of the genes found expressed in T cells TADs encompassing the scleroderma associated SNPs were also found to be differentially expressed in Dolcino’s study, including BSG, FCER2, GPA33, MAP2K7, SCAMP2, and TSPAN33." (PMID 33894768, 2021).
cancer (3 papers, 2021 to 2025). A tumor composed of atypical neoplastic, often pleomorphic cells that invade other tissues. "Additionally, we found a significant correlation between the expression of SCAMP2 and the sensitivity to various anti-cancer drugs, including cisplatin." (PMID 40406117, 2025). "Given the importance of Cav3.2 channels in the development of peripheral painful neuropathies, it will be interesting to assess to what extent SCAMP2-mediated regulation of Cav3.2 could possibly contribute to cancer-related neuropathic pain." (PMID 34980194, 2022). "Importantly, altered expression of SCAMP2 has been reported in several types of cancer." (PMID 34980194, 2022).
tumor (2 papers, 2022 to 2025). "Functionally, GSEA analysis revealed that SCAMP2 was associated with multiple tumor-related signaling pathways, including the Notch Signaling Pathway and Cell cycle." (PMID 40406117, 2025). "Considered the tumor size, we determined that secretory carrier-associated membrane protein 2 (SCAMP2) and the other seven proteins were upregulated in both the CT/CN and Large/Small groups." (PMID 36248973, 2022). "Subcutaneous tumors formed in nude mice using T24 cells with stable SCAMP2 overexpression demonstrated significant tumor formation." (PMID 40406117, 2025). "At the end of the experiment, the tumor weight in the SCAMP2 overexpression group was significantly higher than that in the control group." (PMID 40406117, 2025). "The tumor growth curve indicated that following treatment with 10 mg/mL cisplatin, the tumor growth rate in the SCAMP2 overexpression group was significantly higher than that in the control group." (PMID 40406117, 2025). "In the TCGA-BLCA dataset, SCAMP2 expression in tumor tissues was significantly higher than in normal tissues, and low expression of SCAMP2 in samples from both the TCGA-BLCA and GSE32894 datasets was associated with significantly better prognosis compared to high expression samples." (PMID 40406117, 2025).
neurodevelopmental disorder (1 paper, 2014). A behavioral and cognitive disorder with onset during the developmental period that involves impaired or aberrant development of intellectual, motor, or social functions. "Our studies found that CNVs encompassing human CLN3 and SCAMP2 are associated with neurodevelopmental disorders." (PMID 24705017, 2014).
SCAMP2 also shares sentences with these, for which no sentence is quoted: asthenia (1 paper); breast carcinoma (1); cataract (1); Hypertension (1); infection (1); Stroke (1); type 2 diabetes (1).